STAU1 (staufen double-stranded RNA binding protein 1)
Description:
Binds double-stranded RNA (regardless of the sequence) and tubulin. May play a role in specific positioning of mRNAs at given sites in the cell by cross-linking cytoskeletal and RNA components, and in stimulating their translation at the site. (Microbial infection) Plays a role in virus particles production of many viruses including of HIV-1, HERV-K, ebola virus and influenza virus. Acts by interacting with various viral proteins involved in particle budding process.
Synonyms: STAU; PPP1R150
Tractability: Antibody: its Gene Ontology location is reachable by antibodies, with high confidence. PROTAC: ubiquitination databases record sites on it; its protein half-life has been measured.
Gene: Protein-coding gene on chromosome 20 (49,113,338 to 49,188,417, reverse strand). Ensembl gene ENSG00000124214.
Subcellular location: Cytoplasm; Rough endoplasmic reticulum
Subcellular location (Human Protein Atlas): Cytosol
Gene Ontology:
Molecular function: protein binding; RNA binding; double-stranded RNA binding; mRNA binding; protein phosphatase 1 binding
Biological process: positive regulation by virus of viral protein levels in host cell; positive regulation of viral genome replication; anterograde dendritic transport of messenger ribonucleoprotein complex; germ cell development; intracellular mRNA localization; lncRNA-mediated post-transcriptional gene silencing; protein localization to synapse; cellular response to oxidative stress; modification of postsynaptic structure; modulation of chemical synaptic transmission; positive regulation of long-term synaptic potentiation
Cellular component: cell body; cytoplasm; cytoplasmic ribonucleoprotein granule; cytosol; dendrite; endoplasmic reticulum; extracellular exosome; membrane; plasma membrane; cytoplasmic stress granule; microtubule associated complex; neuron projection; neuronal cell body; rough endoplasmic reticulum; dendrite cytoplasm; glutamatergic synapse; protein-containing complex
Genetic constraint (gnomAD): Loss-of-function variants: 13 observed, 63.16 expected, observed/expected ratio (o/e) 0.21, 90% interval 0.13 to 0.33. The upper end of that interval is the gene's LOEUF score, 0.33, which puts it in group 1 of 6, group 1 being the genes least tolerant of losing a copy. Missense variants: 571 observed, 743.73 expected, observed/expected ratio (o/e) 0.77, 90% interval 0.72 to 0.82. Synonymous variants: 269 observed, 278.71 expected, observed/expected ratio (o/e) 0.97, 90% interval 0.87 to 1.07.
Homologues: Orthologues: macaque STAU1 (99% identical), pig STAU1 (97% identical), chimpanzee STAU1 (95% identical), rabbit STAU1 (94% identical), dog STAU1 (85% identical), tropical clawed frog stau1 (82% identical), guinea pig STAU1 (79% identical), rat Stau1 (78% identical), mouse Stau1 (77% identical), zebrafish stau1 (71% identical), Drosophila melanogaster Zn72D (7% identical), Drosophila melanogaster loqs (7% identical), and 3 more. Paralogues in human: STAU2 (42% identical), ADAR (16% identical), ADARB1 (13% identical), ADAD1 (12% identical), ADARB2 (12% identical), ADAD2 (9% identical), ADAT1 (9% identical), ILF3 (8% identical), STRBP (7% identical), TARBP2 (7% identical), ZFR2 (7% identical), PRKRA (7% identical), and 2 more.
Diseases named in the same sentence as STAU1 in open-access papers:
STAU1 is named in the same sentence as 49 diseases in open-access papers, as found by Europe PMC text mining. Sharing a sentence is not in itself a finding about the gene and the disease. The quoted sentences say what the papers report.
gastric cancer (15 papers, 2016 to 2025). A primary or metastatic malignant neoplasm involving the stomach. "An independent study supported these findings by showing that STAU1-mediated degradation of p21 in HOXA11-AS-overexpressing gastric cancer cells (BGC823 and SGC7901 cell lines) promotes proliferation." (PMID 34633481, 2021). "A similar effect was observed in gastric cancer cells and tumors in which STAU1-mediated degradation of the KLF2 transcription factor, promotes in vitro and in vivo metastasis." (PMID 34633481, 2021). "For example, the TF E2F1 evokes the TINCR transcriptional activity and hastens gastric cancer progression through activating the TINCR/STAU1/CDKN2B axis." (PMID 34721660, 2021). "TINCR/STAU1 complex promotes gastric cancer proliferation by increasing the cell cycle as a result of the depletion of CDKN2B." (PMID 33050646, 2020). "HOXA11-AS1/WDR5, EZH2, and STAU1 boost metastasis in gastric cancer through regulation of their respective target genes." (PMID 33050646, 2020). "In addition, knockdown of STAU1 or overexpression of KLF2 in gastric cancer cells increased expression levels of cyclin-dependent kinases and reduced cell proliferation." (PMID 34633481, 2021). "E2F1 could induce TINCR transcriptional activity and accelerated the progression of gastric cancer by activating the TINCR/STAU1/CDKN2B signaling axis." (PMID 32851080, 2020). "Further studies performed in gastric cancer, confirmed the binding of TINCR to STAU1 protein and found that this interaction induced the STAU1 mediated decay of KLF2 mRNA." (PMID 33466464, 2021). "In gastric cancer cell lines (SGC7901 and BGC823), upregulated TINCR lncRNA forms a ribonucleoprotein complex with STAU1, UPF1, and KLF2 mRNA that promotes SMD of KLF2 transcripts." (PMID 34633481, 2021). "In gastric cancer, lncRNA TINCR regulates cell proliferation and apoptosis through binding to STAU1 to affect KLF mRNA stability." (PMID 28881797, 2017). "Similarly, gastric cancer resists ferroptosis via the PLAGL2-STAU1-NCOA4 axis, where STAU1 destabilizes NCOA4 mRNA, suppressing ferritinophagy and reactive iron accumulation." (PMID 40919170, 2025). "LncRNA TINCR could bind to STAU1, influenced KLF2 mRNA stability, and regulated CDKN1A/p21 expression, thereby affecting proliferation and apoptosis of gastric cancer cells." (PMID 34234860, 2021).
colorectal cancer (10 papers, 2016 to 2023). A primary or metastatic malignant neoplasm that affects the colon or rectum. "STAU1 has been previously identified in colorectal cancer, whereas PHGDH protein has been identified in ovarian cancer." (PMID 37775701, 2023). "Damas and colleagues showed that lncRNA-SNHG5 promotes colorectal cancer cell survival by counteracting STAU1-mediated SPATS2 mRNA destabilization." (PMID 34163032, 2021). "For example, SNHG5 promotes colorectal cancer cell survival by counteracting STAU1-mediated mRNA destabilization." (PMID 30250399, 2018). "Here, the authors identify SNHG5 as a long non-coding RNA promoting proliferation and survival of colorectal cancer cells by protecting specific mRNAs from STAU1-mediated degradation." (PMID 28004750, 2016). "By contrast STAU1 depletion blocks apoptosis and increases survival of colorectal cancer cells." (PMID 34633481, 2021). "Hence, we characterize SNHG5 as a lncRNA promoting tumour cell survival in colorectal cancer and delineate a novel mechanism in which a cytoplasmic lncRNA functions through blocking the action of STAU1." (PMID 28004750, 2016). "In colorectal cancer, SNHG5 interacts with the SPATS2 (spermatogenesis associated serine rich 2) and increases its stability by blocking the mRNA degradation in the cytoplasm, caused by STATS2 mRNA interaction with STAU1 (staufen double-stranded RNA binding protein 1)." (PMID 32318335, 2020). "This is consistent with previous studies in the colorectal cancer HCT116 cells and in the transformed HEK293 cells that showed that Stau1 depletion or knock-out did not impair cell proliferation." (PMID 35008641, 2021).
amyotrophic lateral sclerosis (7 papers, 2018 to 2026). Amyotrophic lateral sclerosis (ALS) is a neurodegenerative disease characterized by progressive muscular paralysis reflecting degeneration of motor neurons in the primary motor cortex, corticospinal tracts, brainstem and spinal cord. "STAU1 becomes highly overabundant in multiple human neurological diseases, including amyotrophic lateral sclerosis (ALS), frontotemporal dementia (FTD), Parkinson’s disease, Alzheimer’s disease and spinocerebellar ataxia type 2 (SCA2); and also increases in response to acute stress." (PMID 41145462, 2025). "In addition, STAU1 forms a protein complex with TDP43, whose mutation is associated with frontotemporal lobar degeneration and amyotrophic lateral sclerosis and this complex regulates the sensitivity of neuronal cells to apoptosis and DNA damage." (PMID 30140277, 2018). "Previously, we showed that its paralog, Staufen1 (STAU1), was overabundant in cellular and mouse models of neurodegenerative diseases and amyotrophic lateral sclerosis (ALS) patient spinal cord." (PMID 39955058, 2025). "We previously showed that lowering STAU1 levels mitigates these disease-related features and prevents neuronal death in animal models of amyotrophic lateral sclerosis/frontotemporal dementia (ALS/FTD) and spinocerebellar ataxia type 2 (SCA2)." (PMID 41145462, 2025). "We identified Staufen1 (STAU1) as an interactor of ATXN2, and showed elevation in cells from SCA2 patients, amyotrophic lateral sclerosis (ALS) patients, and in SCA2 mouse models." (PMID 30194296, 2018).
glioma (7 papers, 2020 to 2023). A benign or malignant brain and spinal cord tumor that arises from glial cells (astrocytes, oligodendrocytes, ependymal cells). "In glioma-derived endothelial cells, Stau1 binds to the ZNF655 mRNA coding for a zinc finger protein following enhanced expression of the lncRNA LINC00346 and thus enhances its degradation via enhanced SMD." (PMID 35008641, 2021). "For example, LINC00665 is downregulated in glioma and mediates STAU1-mediated MTF1 and YY2 stability, affecting malignant biological behavior of glioma." (PMID 32851059, 2020). "LINC00665 in glioma cells can also inhibit tumor progression via STAU1-mediated mRNA degradation." (PMID 35273128, 2022). "Furthermore, as suggested, STAU1 expression levels can also be considered as a potential biomarker for high grade gliomas." (PMID 34633481, 2021). "Additionally, overexpression of TAF15 stabilizes LINC00665, leading to reduced STAU1-mediated mRNA degradation of both MTF1 and YY2, thereby restricting GTSE1 transcription and ultimately disrupting glioma’s malignant progression." (PMID 37403043, 2023). "Hence, STAU1 depletion increased stability and half-life of ZNF331 mRNAs and inhibited glioma progression." (PMID 34633481, 2021). "Similarly, the available survival data for glioma patients show a negative relationship between STAU1 mRNA levels and the 3 year survival rate, supporting its oncogenic role in gliomas." (PMID 34633481, 2021).
viral infection (6 papers, 2017 to 2022). "STAU1 has been found to promote viral replication in several types of viral infections (for example: influenza, human immunodeficiency virus type 1 [HIV-1,], human endogenous retrovirus [HERV-K,], and Ebola)." (PMID 34768809, 2021). "Upon viral infection, in the early stage, Stau1 facilitates viral translation through binding with viral RNA." (PMID 30744035, 2019). "To determine whether STAU1 is recruited into RABV Negri bodies (NBs) upon viral infection, we infected SH-SY-5Y cells with the RABV HEP-Flury strain for 36 h and visualized the localization of endogenous STAU1 by immunofluorescence analysis (IFA)." (PMID 34452292, 2021). "We focused on STAU1 as a novel EBOV host factor that promotes efficient virus infection." (PMID 30301857, 2018). "To determine whether STAU1 is recruited to EBOV inclusion bodies upon viral infection, we performed a time course infection and visualized localization of endogenous STAU1 by immunofluorescence analysis (IFA)." (PMID 30301857, 2018). "Additionally, the reduction of EV-A71-progeny viral RNA was detected in the Stau1 knockout cells, implying that Stau1 could be a positive regulator of viral infection." (PMID 30744035, 2019). "Interestingly, STAU1 is a negative regulator of PKR-mediated translation shutdown, and this functional antagonism is also mutually observed for ADAR1 in the context of virus infection." (PMID 28542129, 2017). "Specifically, we asked whether STAU1 could interact directly or indirectly with VP35 and/or NP in the absence of active virus infection using coimmunoprecipitation (co-IP) assays." (PMID 30301857, 2018).
spinocerebellar ataxia type 2 (4 papers, 2021 to 2026). A subtype of type I autosomal dominant cerebellar ataxia (ADCA type I) characterized by truncal ataxia, dysarthria, slowed saccades and less commonly ophthalmoparesis and chorea. "Based on this, STAU1 depletion has been proposed as a therapeutic approach in spinocerebellar ataxia type 2 (SCA2) mouse model." (PMID 34633481, 2021).
frontotemporal dementia (3 papers, 2018 to 2025). Frontotemporal dementia (FTD) comprises a group of neurodegenerative disorders, characterized by progressive changes in behavior, executive dysfunction and language impairment, as a result of degeneration of the medial prefrontal and frontoinsular cortices. "We had previously found that autophagy is abnormally inhibited in SCA2 patient fibroblasts and cerebellar and spinal cord tissues of SCA2 mouse models, as well as ALS and frontotemporal dementia (FTD) fibroblasts and mouse models associated with overabundance of the RNA binding protein STAU1." (PMID 39156128, 2024).
prostate carcinoma (3 papers, 2021 to 2023). A carcinoma that arises from epithelial cells of the prostate gland. "Similar observations have been reported in prostate cancer cell line LNCaP, indicating that STAU1 downregulation inhibits proliferation of these cells without promoting apoptosis." (PMID 34633481, 2021). "Along those lines, STAU1 has been previously shown to be an unfavorable prognostic marker in prostate cancer." (PMID 34633481, 2021). "In the prostate cancer cell lines PC3 and DU145, elevated STAU1 was associated with increased migration and invasion through FAK signaling." (PMID 34633481, 2021). "This is also observed in prostate cancer, where high levels of Stau1 regulate migration and invasion via the activation of focal adhesion kinase." (PMID 35008641, 2021). "Interestingly, STAU1 was the most altered RBP in both carcinomas, and yet it has never been correlated with COAD or READ; however, it has been associated with prostate cancer." (PMID 37384253, 2023). "Therefore, STAU1 downregulation partially inhibited the motility and metastasis of prostate cancer cells, suggesting that STAU1 targeting may exhibit a therapeutic effect for prostate cancer treatment." (PMID 34633481, 2021).
alveolar rhabdomyosarcoma (2 papers, 2021). A rapidly growing malignant mesenchymal neoplasm. "We have recently reported that in embryonal rhabdomyosarcoma cells (RD), elevated expression of STAU1 is associated with increased cell proliferation." (PMID 34633481, 2021). "In contrast, in embryonic subtypes of rhabdomyosarcoma, high Stau1 expression causes C-MYC translation via post-transcriptional gene regulation and results in significant effects on the proliferative and metastatic potential of these cells." (PMID 35008641, 2021). "In cancer, our recent findings indicated that STAU1 positively impacts autophagy in the alveolar rhabdomyosarcoma cell lines RH30 and RH41 through upregulation of JNK signaling pathway or direct interaction with the mRNA of autophagy-related genes (ATGs)." (PMID 34633481, 2021). "The observed pro-growth effect of STAU1 on rhabdomyosarcoma cells was due, in part, to the increased translation of oncogenic c-myc via direct binding of STAU1 to its mRNA." (PMID 34633481, 2021). "Likewise, in the alveolar rhabdomyosarcoma cell line RH30, STAU1 knockdown causes apoptosis and reduces cancer progression." (PMID 34633481, 2021). "In rhabdomyosarcoma cell lines (RH30 and RD), however, elevated STAU1 promotes cell migration and invasion." (PMID 34633481, 2021).
atherosclerosis (2 papers, 2019 to 2020). A disease characterized by the build-up of fatty material and calcium deposition in the arterial wall resulting in partial or complete occlusion of the arterial lumen. "To interrogate the SMILR:CENPF:STAU1 interaction in human atherosclerosis, we performed an RNA-seq on relatively stable and unstable regions dissected from fresh human carotid plaques obtained at carotid endarterectomy in symptomatic patients." (PMID 31339449, 2019). "Among these genes, only STAU1, SERGEF, and PDGFD are known to be associated with atherosclerosis." (PMID 33381146, 2020).
cognitive decline (2 papers, 2018 to 2022). "Mapping of GWAS results identified genes that have been previously associated with cognitive decline including STAU1, SEMF3A, IP6K1, MST1, the ATNX2/BRAP locus, ALDH2 and DDX27, where a likely functional missense variant is highly associated." (PMID 35052462, 2022). "This step identifies a specific set of largely neuronal genes, such as STAU1 and SEMA3F, predicted to control cognitive decline in older adults." (PMID 30140277, 2018).
colon cancer (2 papers, 2021 to 2022). "STAU1 influences colon cancer expression by regulating RNA subset localization during mitosis." (PMID 35845138, 2022).
depression (2 papers, 2021 to 2025). "The seven positively selected depression-associated genes we identified in the human lineage are involved in brain development (PSEN2, ANKK1, PCDH9) and immunity (STAU1 and LYRM4), as highlighted in our results." (PMID 40075226, 2025). "Several TWAS significant genes were also dysregulated in brains of depression cases compared with controls (including PCDHA8, FANCL, TMEM161B-AS1, GMPPB, STAU1, NDUFA2, GPX1 and PCDHA7), implying that genetic variants may contribute to depression risk by regulating gene expression." (PMID 34021117, 2021). "Interestingly, five TWAS significant genes (TMEM161B-AS1, GMPPB, STAU1, NDUFA2 and GPX1) were significantly upregulated in brains of depression cases compared with controls in GSE102556 dataset." (PMID 34021117, 2021).
glioblastoma (2 papers, 2020 to 2023). The most malignant astrocytic tumor (WHO grade IV). "With a variety of assays, we confirmed that BDNF-AS could bind to STAU1 and reduce the expression and stability of RAX2 mRNA via SMD, thereby further inhibited the malignant behaviors of glioblastoma cells." (PMID 32015336, 2020). "Moreover, BDNF-AS could elicit retina and anterior neural fold homeobox 2 (RAX2) mRNA decay through STAU1-mediated decay (SMD), and thereby regulated the malignant behaviors glioblastoma cells." (PMID 32015336, 2020).
myotonic dystrophy type 1 (2 papers, 2016 to 2025). Steinert disease, also known as myotonic dystrophy type 1, is a muscle disease characterized by myotonia and by multiorgan damage that combines various degrees of muscle weakness, arrhythmia and/or cardiac conduction disorders, cataract, endocrine damage, sleep disorders and baldness. "In myotonic dystrophy type 1 (DM1), STAU1 increases considerably, where it facilitates the translation and nuclear export of mutant mRNAs." (PMID 41561436, 2025). "In our 2012 report, we found that the overexpression of Stau1 was able to reverse key splicing defects, for example, the missplicing of exon 11 of INSR and the intronic retention event in the CLC1 pre-mRNA, in the neuromuscular disorder Myotonic Dystrophy Type 1 (DM1)." (PMID 27695661, 2016).
Obesity (2 papers, 2018 to 2024). Accumulation of substantial excess body fat. "Our study discloses that GIGYF2 mediates obesity-related IR by disrupting the PI3K/AKT signaling axis through the up-regulation of STAU1/PTEN." (PMID 39138413, 2024). "In the current study, we revealed that obesity leads to IR via upregulating GIGYF2 expression, which causes the disruption of the PI3K/AKT pathway through activation of the STAU1-PTEN signaling cascade." (PMID 39138413, 2024). "Based on the in vitro findings that GIGYF2 promotes IR in hepatocytes through the STAU1/PTEN/AKT axis, we therefore further investigated whether GIGYF2 mediates obesity-induced IR in obese mice fed with HFD." (PMID 39138413, 2024).